CCR2 (C-C motif chemokine receptor 2)
Diseases named in the same sentence as CCR2 in open-access papers (continued):
Sharing a sentence is not in itself a finding about the gene and the disease.
Obesity (continued). "CCR2 and CX3CR1 may synergistically impact the inflammatory monocyte phenotypes in obesity." (PMID 35422759, 2022). "Interestingly, in the present study, CCR2 expression was somewhat higher, albeit non-significantly, in PBCs of patients with obesity, and BMI was predictive of CCR2 gene expression levels in PBCs both in controls and patients, and more strongly in the male patients." (PMID 36009555, 2022). "Notably, significant elevations in IL-2 expression in the AT together with that of other inflammatory mediators (IL-8, IL-12A, CCL5, CCL19, CCR2 and CCR5 and TLRs) in obesity suggests that these factors may contribute cooperatively for insulin resistance induction in this population." (PMID 33004937, 2020). "However, besides the CCR2 level, DARC+Ly6Clo ATMs express a higher level of IL-10, IDO, and TGF-β mRNA than those of DARC- cells, indicating that the DARC+Ly6Clo cells essentially function to revert the inflammatory status in diet-induced obesity to an anti-inflammatory status." (PMID 31817755, 2019). "During obesity, ATDC migration tracking has been studied using Ccr7−/− mice, as ATDC migration is specifically dependent on CCR7 but independent of CCR2, whereas monocyte-derived ATMs are dependent on CCR2." (PMID 34445379, 2021). "Our data suggest that obesity could increase TNF‐α and CCR2 in the kidney, when hyperinsulinemia is not present." (PMID 29632818, 2018).
Insulin resistance (93 papers, 2007 to 2025). Increased resistance towards insulin, that is, diminished effectiveness of insulin in reducing blood glucose levels. "Mice with CCR2 deficiency had attenuated deposition of visceral fat and insulin resistance when challenged with a high fat diet." (PMID 29694633, 2018). "The overexpression of CCR2 by M1 macrophages in visceral WAT is associated with insulin resistance and consequently with NAFLD." (PMID 28115795, 2017). "As a final remark we can conclude that an increase of CCL2 serum levels is associated with the polymorphic phenotypes (A+/Ile+) of the polymorphisms G-2518A in CCL2 and Val64Ile in CCR2 in individuals with insulin resistance of Mexican population." (PMID 26839895, 2016). "Combined with its receptor, C-C chemokine receptor type 2 (CCR2), the MCP-1–CCR2 system is closely associated with hepatic steatosis and insulin resistance in obese patients." (PMID 27563875, 2016). "MCP-1-or CCR2-deficient mice fed a high-fat diet exhibited fewer macrophages and a lower inflammatory gene profile in adipose tissue together with reduced insulin resistance." (PMID 25789857, 2015). "Air pollution–mediated susceptibility to inflammation and insulin resistance: influence of CCR2 pathways in mice." (PMID 24149114, 2014). "Furthermore, endotoxin is also known to markedly induce MCP-1 which can recruit the C-C motif chemokine receptor-2 (CCR2)-expressing monocytes in adipose tissue, and CCR2 associates adipose tissue inflammation and systemic insulin resistance." (PMID 25328713, 2014). "The development of insulin resistance and type 2 diabetes is significantly influenced by macrophage recruitment into adipose tissue via CCR2." (PMID 39125901, 2024). "It is now demonstrated that insulin resistance, pro-inflammatory macrophage accumulation, and adipose tissue inflammation are dependent on CCR2-dependent monocyte recruitment." (PMID 39544233, 2024). "These mouse models have previously not shown any metabolic traits – i.e., glucose intolerance or insulin resistance – on a chow diet (CCR2-/- and Rag2-/- mice)." (PMID 37400850, 2023). "CCL2, along with its cognate receptor C-chemokine receptor (CCR)-2, forms a CCL2-CCR2 complex leading to the recruitment and accumulation of macrophages and, subsequently, insulin resistance and hepatic steatosis in obese patients." (PMID 35327352, 2022). "We did not observe significant correlations between monocyte subsets expressing CCR2+ with IMT or insulin resistance levels in female children, even those with IMT ≥ p75." (PMID 36286282, 2022). "It was our rationale behind estimating insulin resistance in our cohort of obese children, analyzing potential associations of monocyte subsets, expressing CCR2 with IMT and insulin resistance." (PMID 36286282, 2022). "The chemokine ligand 2 (CCL2)–CC chemokine receptor type 2 (CCR2) axis plays a critical role in the egress of Ly6C+ inflammatory monocytes from the bone marrow (BM) to the gut mucosa and is involved in insulin resistance." (PMID 34444972, 2021). "Resveratrol, a flavonoid found in red wine, decreased insulin resistance, inflammation, and CCR2-driven macrophage infiltration in SAT and VAT in HFD-fed mice." (PMID 32471061, 2020). "Genetic loss of MCP-1 or CCR2 decreases the adipose tissue macrophage content, reduces inflammation, and protects mice from HFD-induced insulin resistance." (PMID 32437400, 2020). "Given that macrophage infiltration and insulin resistance in adipose tissues is mainly mediated by the CCL2/CCR2 chemotaxis system, we further conducted immunofluorescence and Western blot analysis to examine CCL2 protein levels in epididymal adipose tissue." (PMID 32979037, 2020). "In response to the CL diet, the resulting influx of Ccr2-positive cells and liver-resident macrophages (Kupffer cells) produces a large amount of proinflammatory mediators and promotes insulin resistance and NASH in mice." (PMID 31965018, 2020).
Insulin resistance (continued). "Pharmaceutical inhibition of CCR2 improves insulin resistance and hepatic steatosis in db/db and diet-induced obese mice." (PMID 32437400, 2020). "Our data showed that CCR2 depletion attenuated insulin resistance, hyperlipidemia, and fat accumulation induced by HFD, although CCR2 depletion did not significantly reduce body weight." (PMID 31498850, 2019). "CC-chemokine receptor 2 (CCR2) induced systemic cellular inflammatory responses play a critical role in diet-induced insulin resistance." (PMID 29966381, 2018). "CCR2 is involved in the macrophage recruitment to the liver in obese mice, which contributes to insulin resistance." (PMID 30254630, 2018). "The interaction of MCP-1 with its receptor CCR2 is considered pivotal in obesity-induced insulin resistance." (PMID 29694633, 2018). "This is of importance, given that the MCP-1/CCR2 axis plays a central role during the promotion of adipose tissue MF recruitment and insulin resistance." (PMID 29513874, 2018). "A murine model has exhibited that both MCP-1-deficient and MCP-1 receptor CCR2-deficient mice are protected against inflammation and macrophage accumulation in adipose tissue and display resistance to DIO-caused insulin resistance." (PMID 30425746, 2018). "We have previously suggested that CCR2 is important in PM2.5 exposure-mediated inflammation leading to insulin resistance under high fat diet situation." (PMID 28253935, 2017). "This study investigated the effects of α-mangostin on insulin resistance and fatty liver in high fat diet-induced obese mice through the regulation of CCR2." (PMID 28598982, 2017). "Recent studies in mice have suggested uniformly that blockade of the CCL2 receptor CCR2 will lead to an improvement of insulin resistance and glycaemic control." (PMID 28186566, 2017). "The present study assessed the importance of CCR2 in PM2.5 exposure-induced insulin resistance in the context of normal diet." (PMID 28253935, 2017). "CC-chemokine receptor 2 (CCR2) appears to be essential in diet-induced insulin resistance implicating an important role for systemic cellular inflammation in the process." (PMID 28253935, 2017). "Both MCP-1-deficient mice and MCP-1 receptor CCR2-deficient mice are protected against macrophage accumulation and inflammatory responses in adipose tissues and are resistant to DIO-induced insulin resistance." (PMID 27148161, 2016). "Several groups have reported that CCR2- and MCP-1-deficient mice exhibit decreased ATM content, attenuated inflammation in adipose tissue, and protection against HFD-induced insulin resistance." (PMID 26197341, 2015). "Overexpression of the pro-inflammatory cytokine MCP-1 in adipose tissue induces whole-body insulin resistance whereas inhibiting the expression of MCP-1 or its receptor CCR-2, protects mice from developing high-fat-diet–induced insulin resistance." (PMID 26340264, 2015). "This upregulation is similar to what has been observed in the WAT and suggest that MCP1 responsive, i.e. CCR2+ macrophages, are recruited to skeletal muscles, where they further worsen insulin resistance." (PMID 25337938, 2014). "In contrast, MCP-1 or its receptor CCR-2 knockout mice have fewer macrophages and less inflammation in adipose tissue and are protected from high-fat-diet-induced insulin resistance." (PMID 23533500, 2013). "Antagonism of the chemokine receptor CCR2 has been investigated in various fields of experimental cardiology and vascular medicine, including inhibition of restenosis, diet-induced insulin resistance, and hypertensive atherosclerosis; here, we examined its possible applicability to post-MI therapy." (PMID 40606572, 2025). "The strong mobilization of these cells by C-C chemokine receptor type 2 (CCR2) may contribute to insulin resistance/type 2 diabetes in adipose inflammation tissue." (PMID 38045957, 2023).
Insulin resistance (continued). "Furthermore, CVC ameliorated insulin resistance, hepatic inflammation, and fibrosis attributed to an efficient inhibition of CCR2+ monocyte recruitment." (PMID 36845555, 2023). "In another study, scientists observed that CD11c+ ATM ablation could reduce adipose tissue inflammatory gene expression and improve insulin resistance in the Ccr2 KO mice model." (PMID 35757707, 2022). "Therefore, utilizing CCR2 inhibitors to regulate macrophages to improve insulin resistance requires the support of more clinical trial data." (PMID 35757707, 2022). "CX3CR1 and CCR2 may independently regulate monocyte phenotype and macrophage polarization, and contribute to adipose tissue inflammation and insulin resistance, and the progression of NAFLD." (PMID 34360773, 2021). "Taken together, these data suggest that CCR2 inhibitors might be beneficial for patients with glycaemia and insulin resistance, but further studies are required, as has been indicated previously." (PMID 32704573, 2020). "The over-expression of CCL2 in adipose tissue increases macrophage recruitment, whereas a reduction of CCL2 or its receptor CCR2 lowered proinflammatory macrophages accumulation in the adipose tissue and provides protection from insulin resistance as well as hepatic steatosis." (PMID 32708964, 2020). "The effect of CCR2 depletion on insulin resistance and secretion." (PMID 31498850, 2019). "Increasing evidence has shown that CCR2 could promote the macrophage recruitment and infiltration of tissue in the pathogenesis of insulin resistance." (PMID 29967759, 2018). "Furthermore, previous studies have shown that the CCR2 inhibitor propagermanium can prevent insulin resistance and steatosis in db/db mice and wild-type mice." (PMID 28076416, 2017). "The critical role of MCP-1 in the diabetic condition has been demonstrated in studies showing that its overexpression in adipocytes leads to tissue inflammation and insulin resistance, while mice deficient in MCP-1 or its receptor C-C motif chemokine receptor-2 (CCR-2) reverse the condition." (PMID 28115020, 2017). "Pdpk1 also inhibits Ccr2, M1 macrophages, and insulin resistance." (PMID 28731442, 2017). "The CCL2/CCR2 axis is a major component of insulin resistance in obese mice." (PMID 20936118, 2010). "In addition, dual CCR2/CCR5 antagonism could ameliorate insulin resistance and inflammation in high-fat diet-fed mice and decrease CCL2/CCL4‐induced migration of macrophage." (PMID 33968046, 2021). "Additionally, experimental studies have shown that CCR2 and CCL2-deficient mice exhibited attenuated inflammation in adipose tissue, decreased adipose tissue macrophages, and protection against high fat diet-induced insulin resistance." (PMID 33042108, 2020). "While the M1 phenotype stimulates the generation of inflammatory cytokines such as TNF-α, iNOS, CCR2, and IL-12, the M2 phenotype promotes anti-inflammatory cytokines like IL-4 and IL-13, which relieve inflammatory reactions and inhibit the development of insulin resistance." (PMID 31212747, 2019). "Our study further demonstrated that RES administration could reverse insulin resistance, decrease CCR2 expression in SAT and VAT, and reduce inflammation and macrophage infiltration of SAT and VAT, thus increasing insulin signaling molecules (such as IRS-1, GLUT4 and pAkt) in HFD-induced obese mice." (PMID 29967759, 2018). "In HFD-fed CCR2-/- male mice, PM2.5 enhanced insulin resistance through the regulation of hepatic lipid metabolism, inflammatory responses in visceral adipose tissue, and glucose utilization in skeletal muscle through both CCR2-dependent and independent pathways." (PMID 29966381, 2018). "Furthermore, although Ccr2−/− mice fed a HFD have fewer macrophages in their WAT than WT mice, the CCR2 deficiency does not normalize ATM content or insulin resistance to the levels of lean animals." (PMID 26197341, 2015).
Insulin resistance (continued). "Transgenic expression of CCL2 in adipose tissue increases macrophage infiltration, inflammation, and insulin resistance, whereas knockdown of CCL2 or CCR2 impairs the migration of macrophages into adipose tissue." (PMID 37457301, 2023). "Accordingly, the genetic deletion or pharmacological inhibition of CCR2 has been reported to improve NASH and insulin resistance in mice." (PMID 35744024, 2022). "• T cell activation. • Induction of inflammatory molecules like IL8, IL12A, CCL5, CCL19, CCR2, and CCR5. • Contribution to increased insulin resistance secondary to TLR2, TLR4, and TLR10 interaction." (PMID 35422689, 2022). "Various mouse models deficient in (functional) genes important for ATM recruitment, such as Tnf-α or Ccr2, are protected from HFD-induced insulin resistance." (PMID 28932870, 2018). "Blockade of CCR2, a chemokine receptor for ligands CCL2, 7, 8, 13, and 162, has been reported to improve insulin resistance, lipid metabolism, and diabetic nephropathy in type 2 diabetic mice." (PMID 26648169, 2015). "Overexpression of MCP-1 enhances macrophage accumulation and insulin resistance, whereas MCP-1 or its receptor (CCR2) knockout in mice reduces macrophage infiltration in adipose tissue." (PMID 24918199, 2014). "In moderate dose endotoxemia, we observed strong induction of subcutaneous adipose TNF and IL-6 as well as MCP-1, which is known to recruit CCR-2 expressing monocytes, increase inflammatory-M1 adipose tissue macrophage (ATM) and promote insulin resistance." (PMID 22709547, 2012). "Moreover, treatment with PF4178903, another dual CCR2/CCR5 antagonist, reduces adipose tissue macrophage infiltration, lowers serum proinflammatory cytokines levels, and improves insulin resistance and glucose intolerance in mice fed a high-fat diet." (PMID 39457105, 2024). "Tregs are abundant in the lean adipose tissue of mice, but their number was significantly lower in the insulin resistance animal model due to decreased CCR1, CCR2, and CXCR6 expression, which might be responsible for the Treg-specific accumulation." (PMID 31297120, 2019). "However, RES treatment alleviated insulin resistance, increased the expressions of pAkt, GLUT4 and IRS-1 in WAT, and decreased serum proinflammatory cytokine levels, macrophage infiltration and CCR2 expression in WAT." (PMID 29967759, 2018). "Several groups have reported that mice with targeted deletions in the genes for MCP-1/CCL2 and its receptor CCR2 have reduced adipose tissue macrophage (ATM) content, decreased inflammation in fat and protection from high-fat (HF) diet-induced insulin resistance." (PMID 29694633, 2018). "Our study indicates that CCR2 in WAT may play a critical role in macrophage infiltration and the inflammatory response during the development of insulin resistance in HFD-induced obese mice." (PMID 29967759, 2018). "While CCR2 deficiency reduced adipose macrophage content in the PM2.5-exposed animals, it did not improve systemic insulin resistance." (PMID 28253935, 2017). "For instance, mouse models with genetic deletion of MCP-1 or CCR2 have shown that these factors control the infiltration of macrophages into WAT and are crucial for the development of insulin resistance and hepatic steatosis in high-fat diet (HFD)-induced obese mice." (PMID 28076416, 2017). "The subsequent CCR2 intervention experiment showed that early, but not late, propagermanium treatment attenuated insulin resistance." (PMID 28076416, 2017). "CCR2 deletion failed to attenuate PM2.5 exposure-induced insulin resistance in mice fed on normal diet." (PMID 28253935, 2017). "Also, our previous study demonstrated that the inhibition of CCR2 improved NAFLD and insulin resistance." (PMID 28598982, 2017). "In MCP-1 or CCR2 knockout mice, there is a decrease in macrophage infiltration in adipose tissue whereas overexpressing CCL2 enhances macrophage accumulation and insulin resistance." (PMID 23637889, 2013).
Insulin resistance (continued). "Also, it remains to be established whether the two C-C chemokine receptors, CCR2 and CCR5, play common or unique roles in obesity-induced adipose tissue inflammation and insulin resistance." (PMID 24455420, 2013). "Moreover, both CCR5 and CCR2 expression levels correlate significantly with CD14+/CD16+ monocyte subset, and metabolic abnormalities such as dyslipidemia and insulin resistance, have been also reported to promote an inflammatory phenotype in circulating monocytes." (PMID 22645407, 2012). "In addition, the administration of a novel CCR2 antagonist ameliorated insulin resistance in mice fed a high-fat diet without affecting macrophage infiltration into adipose tissue." (PMID 20936118, 2010). "Furthermore, HFD-fed MCP-1 receptor i.e., CCR2-deficient mice (namely, ccr2−/− mice) do not normalize ATM content and insulin resistance to the levels of lean animals, suggesting that ATM recruitment and insulin resistance are also regulated by MCP-1/CCR2 independent signaling pathways." (PMID 24455420, 2013). "The CCR2+ cell percentage and CCR2 expression in the three monocyte subsets significantly correlated with increased IMT and insulin resistance in boys but not girls, where the CCR2+ nonclassical monocyte percentage had the strongest associations (r = 0.73 and r = 0.72, respectively)." (PMID 36286282, 2022).